TMEM106B (transmembrane protein 106B)
Diseases named in the same sentence as TMEM106B in open-access papers (continued):
Sharing a sentence is not in itself a finding about the gene and the disease.
Alzheimer disease (continued). "Until recently, growing evidence highlights the role of TMEM106B in Alzheimer’s disease (AD)." (PMID 33461566, 2021). "In 2012 it was reported that TMEM106B SNPs might be also critical for the pathological presentation of Alzheimer disease." (PMID 30332472, 2018). "In neurodegeneration (including Alzheimer’s disease (AD), FTLD-TDP, etc.)the expression of the microRNA132/212 cluster is decreased, suggesting an upregulation of TMEM106B expression in disease." (PMID 36056242, 2022). "Although TMEM106B variants were initially identified as risk factors for FTLD, recent studies suggest that it may have more general involvements in neurodegenerative diseases including Alzheimer disease, and other in carriers of C9ORF72 expansions such as amyotrophic lateral sclerosis (ALS)." (PMID 30332472, 2018). "The donor brain used for these tomograms had a high level of Alzheimer’s disease neuropathologic change, including a severe burden of tau and amyloid-β with TMEM106B present in the absence of TDP-43 or α-synuclein aggregates in the middle frontal cortex." (PMID 38531877, 2024). "Importantly, we also find convergent phenotypes that reveal potentially novel biological contributions of TMEM106B to TDP-43 nuclear clearance in C9-ALS and tau pathology in Alzheimer’s disease." (PMID 39606446, 2024). "We determined that the transmembrane protein 106B (TMEM106B), normally lysosome-associated, is insoluble in RRMS plaques relative to normal-appearing white matter from individuals with Alzheimer’s disease and non-neurologic controls." (PMID 37443768, 2023). "TMEM106B haplotypes were also shown to associate with the development of cognitive impairment in amyotrophic lateral sclerosis (ALS) and with the presence of TDP-43 pathology in Alzheimer’s disease (AD) and elderly individuals without FTLD." (PMID 29970152, 2018). "To further investigate whether TMEM106B is involved in the clinical progression of Alzheimer’s disease, we turned to the cross-sectional ROSMAP cohort, which includes cognitively unimpaired individuals and individuals with mild cognitive impairment (MCI) and Alzheimer’s disease (AD)." (PMID 38674351, 2024). "Indeed, TDP-43 pathology, like TMEM106B aggregation, is not unique to ALS or ALS/FTD; TDP-43 cytoplasmic mislocalization and aggregation has been observed in Alzheimer’s disease and other types of dementia, as well as in cognitively normal aged populations." (PMID 39606446, 2024).
dementia (24 papers, 2018 to 2025). Loss of intellectual abilities interfering with an individual's social and occupational functions. "In donors < = 65, TMEM106B risk was associated with higher odds of dementia (OR = 6.912 [95% CI 2.015–23.705], p = 0.002)." (PMID 41264095, 2025). "On the other hand, in those < = 65 years of age, TMEM106B risk was associated with increased odds of dementia and was equivalent to 27 years of playing contact sports." (PMID 41264095, 2025). "The protective Ser185 variant is associated with more rapid TMEM106B turnover in lysosomes and lower TMEM106B protein levels, again indicating that the dementia risk alleles are associated with higher TMEM106B." (PMID 37726834, 2023). "Our data implies that TMEM106B is one of a growing list of major dementia risk genes that affect glial lipid metabolism." (PMID 36711721, 2023). "Our data suggests that TMEM106B is one of a growing list of major dementia risk genes that affect glial lipid metabolism." (PMID 37726834, 2023). "Lysosomal protein TMEM106B was increased with the greatest effect size, and this was specific to carriers of the rs1990622-A dementia risk allele." (PMID 37726834, 2023). "ANOVA was used to test the effect of major dementia risk alleles in the TMEM106B and APOE genes on the hippocampal proteome and lipidome, adjusting for age, gender, and post-mortem interval." (PMID 36711721, 2023). "Increased hippocampal TMEM106B with ageing is driven by the rs1990622-A dementia risk allele in the TMEM106B gene, which was associated with increased levels of sarkosyl-insoluble, fibrillar TMEM106B." (PMID 37726834, 2023). "Treatments that converge on reacidifying lysosomes have shown promise in whole animal models of LSDs and dementia, where risk factors for dementias such as the lysosomal size-determinant TMEM106B have been found to stabilize the V-ATPase at the lysosome." (PMID 32515674, 2021). "The TMEM106B variant associated with dementia, rs1990620, was replicated with submodule eigengene expression in three out of four brain regions (DLPFC, TCX, PHG) in the AMP-AD cohorts." (PMID 32492070, 2020). "In those < = 65, TMEM106B risk was related to the presence of dementia." (PMID 41264095, 2025). "There are no functional annotations which elucidate how the BIN1 locus might be impacting AD through regulation or modification of TMEM132C, however, TMEM106B is a known dementia-associated gene which has functions in lysosome function and homeostasis." (PMID 38883718, 2024). "Additionally TMEM106B, which had a particularly notable spatial genetic effect, has a known association to a form of dementia." (PMID 36848389, 2023). "The C‐terminal (CT) domain of TMEM106B occurs as fibrillar protein deposits in the brains of dementia patients." (PMID 39711302, 2025). "In this work, we identified NBP1-91311 as a reliable antibody for directly binding to TMEM106B fibrils extracted from brain tissues of patients with Parkinson’s disease with dementia (PDD) and a 101-year-old normal elder." (PMID 39872397, 2024). "Having shown the neuron killing propensity of TMEM106B CT aggregates, exploring the interplay between TMEM106B and other common proteinopathies appears the logical next step in investigating the molecular basis of multiple etiology dementia." (PMID 38915598, 2024). "One possible pathologic mechanism for the TMEM106B-dementia relationship comes from the relationship between TMEM106B and PSD-95 protein levels." (PMID 30390709, 2018). "Having shown the neurotoxic potential of TMEM106B in transgenic C. elegans, exploring the interplay between TMEM106B and other common proteinopathies appears the logical next step in investigating the molecular basis of multiple etiology dementia." (PMID 39711302, 2025). "Here, we provided evidence that both eQTLs and pQTLs of TMEM106B may decrease the possibility of reaching the top 1% extreme longevity by dementia." (PMID 40211681, 2025).
dementia (continued). "In a pathological group with a history of RHI the TMEM106B risk genotype was associated with worse CTE and TDP-43 inclusions in older individuals and increased risk of dementia in younger individuals, suggesting distinct mechanisms influenced by this variant across the lifespan." (PMID 41264095, 2025). "Notably, the TMEM106B fibril load in the brains of Parkinson’s disease with dementia patients was significantly higher than in age-matched elders." (PMID 39872397, 2024). "In this regard, an important question is whether higher TMEM106B with ageing sensitizes to, or protects against, dementia." (PMID 37726834, 2023). "A SNP in the 3’ untranslated region of TMEM106B (rs1990622-A) is associated with increased risk for AD, FTD, Parkinson’s disease, HS-ageing, and LATE, and is in perfect linkage disequilibrium with other SNPs in the TMEM106B gene that modify dementia risk." (PMID 37726834, 2023). "One of these studies reported a significant association of fibrillar TMEM106B with rs1990622 genotype, but had too few control subjects to determine this association in subjects without dementia." (PMID 37726834, 2023). "Finally, TMEM106B genotype was related to dementia status, adjusting for age at death and duration of football play." (PMID 30390709, 2018). "In a series of former American football players with neuropathologically confirmed CTE, we found that rs3173615, a coding SNP in TMEM106B that was previously implicated with risk of FLTD-TDP, was associated with p-tau density, CD68 density, synaptic loss, and dementia status in case-only analyses." (PMID 30390709, 2018). "The purpose of this study was to determine whether genetic variation in TMEM106B is associated with CTE risk, pathological features, and ante-mortem dementia." (PMID 30390709, 2018). "TMEM106B has been previously linked with dementia, albeit not in preceding LOAD GWAS." (PMID 38356889, 2024). "Even without dementia, amyloid plaques alone can cause a rise in TMEM106B mRNA levels (PA)." (PMID 38674351, 2024). "In zebrafish, THSD7A may have a role in the neurovasculature, and THSD7A has been related to educational attainment; in recent research using GWAS summary statistics, TMEM106B/THSD7A were reported as pleiotropically related to dementia and major depression disorder." (PMID 39169872, 2024). "A recent GWAS for AD and related dementias (ADRD), which pooled AD cases with “proxy cases” having a family history of all-cause dementia, used colocalization analysis to provide evidence that ADRD and FTD with TDP-43 inclusions share causal variants at the TMEM106B and GRN loci." (PMID 37328865, 2023). "Within the full sample, there were no significant TMEM106B associations for CTE status, CTE stage, or dementia." (PMID 41264095, 2025). "Furthermore, TMEM106B variants are significantly correlated with the transcriptional signature of biological aging, cognition, brain volume, and levels of neuronal markers and neuronal proportion specifically in aged cohorts without clinical diagnosis of dementia." (PMID 39606446, 2024). "Whereas some dementia-related proteins were detected (Aβ peptide and α-synuclein protein), others were not (TDP-43, TMEM106B, and tau proteins)." (PMID 37674727, 2023).
amyotrophic lateral sclerosis (18 papers, 2014 to 2025). Amyotrophic lateral sclerosis (ALS) is a neurodegenerative disease characterized by progressive muscular paralysis reflecting degeneration of motor neurons in the primary motor cortex, corticospinal tracts, brainstem and spinal cord. "The aim of this work was to assess the impact of the TMEM106B rs1990622 (A–major risk allele; G–minor allele) on phenotypic variability of 865 patients with amyotrophic lateral sclerosis." (PMID 36012536, 2022). "Until recently, growing evidence highlights the role of TMEM106B in other neurological processes including hippocampal sclerosis of aging, neuronal loss, cognitive deficits, better residual cognition, AD, Parkinson’s disease, and amyotrophic lateral sclerosis." (PMID 33461566, 2021). "A recent study showed that TMEM106B genotypes influence the development of cognitive impairment in amyotrophic lateral sclerosis (ALS) patients." (PMID 24684749, 2014). "Overall, we found that TMEM106B is a disease modifier of amyotrophic lateral sclerosis, whose phenotypic effects encompass both sites of onset and functional status (major risk allele), motor functions (both major risk and minor alleles), and cognition (minor allele)." (PMID 36012536, 2022). "More recently, TMEM106B has been shown to be a genetic modifier in patients with FTLD with C9ORF72 expansions, which are the most common known genetic cause of frontotemporal dementia (FTD), amyotrophic lateral sclerosis, and the combination of these diseases." (PMID 26651479, 2015). "In amyotrophic lateral sclerosis (ALS), multiple ALS-related proteins, including TBK1, GRN, C9orf72 and TMEM106B, are implicated in endosomal sorting and endosomal lysosomal function." (PMID 38239560, 2023). "Subsequently, TMEM106B polymorphisms have been associated with FTLD caused by C9orf72 mutations, cognitive impairment in Amyotrophic lateral sclerosis (ALS) and Parkinson’s disease (PD), and Alzheimer’s disease (AD)." (PMID 35287730, 2022). "TMEM106B is associated with brain aging; myelination disorders; and several neurodegenerative diseases, including frontotemporal lobar degeneration (FTLD), amyotrophic lateral sclerosis (ALS), Alzheimer’s disease, and Parkinson’s disease." (PMID 37421949, 2023). "TMEM106B has also been reported to modulate patients’ cognitive functions in other neurodegenerative diseases, such as Alzheimer’s Disease (AD), Parkinson’s Disease (PD), and amyotrophic lateral sclerosis (ALS)." (PMID 37563705, 2023). "Amyotrophic lateral sclerosis (ALS) and frontotemporal dementia share genetic disruptions (for example, C9orf72, OPTN, VCP, TMEM106B and progranulin (PGRN)) that impair normal Golgi–endolysosomal trafficking, severely reducing intracellular protein handling and degradation capabilities." (PMID 41254240, 2025). "While it does not directly trigger disease development, TMEM106B is linked to TAR DNA-binding protein (TDP-43) pathology and cognitive issues in amyotrophic lateral sclerosis (ALS)." (PMID 39872397, 2024). "By quantitative reverse transcription (RT)-PCR (qPCR), western blot and immunohistochemistry, we studied TMEM106B and PGRN expression levels in a series of AD and control brains, including amyotrophic lateral sclerosis, Parkinson’s disease, multiple system atrophy and non-neurological cases." (PMID 24684749, 2014).
depression (14 papers, 2018 to 2025). "Drug target MR identified causal associations of genetically predicted TMEM106B level on depression (OR = 0.92, 95% CI = 0.90−0.94, p=2.04 ×10−12) and stroke (OR = 0.90, 95% CI = 0.86−0.95, p=3.53 ×10−5)." (PMID 40949012, 2025). "Through pleioFDR, we identified a SNP in the TMEM106B gene, which was significantly associated with AD (B = −0.002, p = 9.1 × 10–4) and depression (B = 0.007, p = 3.2 × 10–9) in the UKB." (PMID 34290577, 2021). "Our study is the first to associate increased TMEM106B levels with aberrant neurotrophin signaling in vivo which could potentially explain its genetic link to mood disorders such as depression." (PMID 40269985, 2025). "For TMEM106B (Transmembrane Protein 106B), a locus previously linked to both depression and coronary artery disease, we observed genome-wide significance in the LGF, strong association with comorbid traits (p-value = 8.0e-10) but only marginal evidence in CVD traits (p-value = 1.1e-03)." (PMID 41299637, 2025). "Previous protein-wide and transcriptome-wide MR have consistently identified TMEM106B as a candidate causal gene for depression, and our results further identify its role in the development of stroke consolidating findings from a previous cross-trait meta-analysis." (PMID 40949012, 2025). "In particular the corpus callosum was implicated by our analyses, in line with previous neuroimaging findings on TMEM106B, with higher volume of several callosal subregions for carriers of the rs5011436 c-allele, the allele that we found to convey risk for depression and to be protective for AD." (PMID 34290577, 2021). "TMEM106B’s importance in brain health is further highlighted by its connections to cognition and mood disorders, such as depression." (PMID 40269985, 2025). "Despite the absence of evidence for drug development specifically targeting TMEM106B in depression or stroke, this gene nonetheless emerges as a prioritized and promising shared drug target for the two conditions." (PMID 40949012, 2025). "Only the TMEM106B locus was shared between depression and stroke, although with different, yet highly correlated lead SNPs (rs6460906 for depression and rs7808568 for stroke, r2 = 0.96)." (PMID 40949012, 2025). "Three of these genes (NEGR1, TMEM106B, HNF1A) have been linked to each of the three diseases (CAD, T2D and depression) in previous studies, supporting their probable involvement in psycho-cardiometabolic multimorbidity." (PMID 37390107, 2023). "For both TMEM106B and ATP2A1, the colocalization analysis showed that the same causal SNP was likely affecting both the risk of anxious or weight gain depression and transcription." (PMID 34158615, 2021). "Local genetic correlation analysis from a recent study further revealed four GWAS loci (e.g. the TMEM106B locus at chr7 or rs13237518) that are shared between depression and AD, five loci shared between schizophrenia and AD, and two loci shared between bipolar and AD." (PMID 41466307, 2025). "Recent research underscored a common single nucleotide polymorphism in the transmembrane protein 106B (TMEM106B) gene which was significantly associated with AD and depression, highlighting the need for further exploration of the complex genetic link between AD and depression." (PMID 39940989, 2025). "Evidence for the involvement of TMEM106B in depression is also compelling." (PMID 34859065, 2021). "The evidence for involvement of TMEM106B in both disorders is further substantiated by our neuroimaging analyses, indicating effects on several brain regions that have been tied to both AD and depression." (PMID 34290577, 2021). "Specifically, the TMEM106B locus was not only identified by both cross-trait meta-analysis at the variant-based association and TWAS at the gene-based association to be shared between depression and stroke, but MR pinpointed its encoding protein as a shared drug target." (PMID 40949012, 2025).
depression (continued). "TWAS analysis identified three significant tissue–gene pairs shared between depression and stroke, including TMEM106B in the transverse colon, FES in the heart atrial appendage, and FES in the stomach, which were also shared between depression and ischemic stroke." (PMID 40949012, 2025). "The genes that are potentially of interest for the study of depression include the Neural Growth Regulator 1 (NEGR1), the glutamate metabotropic receptor 5 (GRM5), the glutamate ionotropic receptor kainate type subunit 3 (GRIK3) and the transmembrane protein 106B (TMEM106B) protein coding genes." (PMID 29662059, 2018). "We identified two transcriptome-wide significant signals: TMEM106B for depression with anxiety (panel CMC DLPFC splicing, p = 1.23 × 10−6) and ATP2A1 for depression with weight gain (panel PsychENCODE, p = 1.34 × 10−6); no significant features were identified for TRD." (PMID 34158615, 2021).
Parkinson disease (14 papers, 2014 to 2025). A progressive degenerative disorder of the central nervous system characterized by loss of dopamine producing neurons in the substantia nigra and the presence of Lewy bodies in the substantia nigra and locus coeruleus. "Colocalization with Alzheimer’s and Parkinson’s disease GWAS implicated SVs at multiple loci, including TMEM106B, BIN3, and NBEAL1." (PMID 41282933, 2025). "Single nucleotide polymorphisms (SNPs) in TMEM106B have since been identified as risk modifiers for a variety of neurodegenerative diseases including AD, hippocampal sclerosis (HS), and Parkinson’s Disease (PD)." (PMID 38915598, 2024). "For example, one recent study showed that TMEM106B knockdown is neuroprotective in both in vitro and in vivo Parkinson’s disease models, and another study found that loss of TMEM106B exacerbates tau pathology and neurodegeneration in an FTD model." (PMID 39606446, 2024). "A contribution of TMEM106B fibrils to disease may also present itself more as a disease modifier where the formation of TMEM106B fibrils contributes to disease manifestation, for example modifying cognitive decline in Parkinson’s disease and ALS." (PMID 36056242, 2022).